AFP (alpha fetoprotein)
Diseases named in the same sentence as AFP in open-access papers (continued):
Sharing a sentence is not in itself a finding about the gene and the disease.
liver cirrhosis (continued). "Meanwhile, HCC usually occurs in the background of liver cirrhosis and is typically accompanied by elevated serum alpha-fetoprotein level." (PMID 37664063, 2023). "Among these patients, 110 (76.3%) were HBsAg positive, and 93 (64.5%) presented with liver cirrhosis at the time of diagnosis, 55 patients had serum AFP levels ≥ 400, and the median tumor size was 5.05 cm (ranging from 1.0 to 16.0 cm)." (PMID 37208618, 2023). "The nomograms for OS and RFS prediction incorporated independent risk factors that were identified through multivariate Cox regression analysis, including tumor diameter, liver cirrhosis, serum AFP levels, and CENPB protein expression." (PMID 37925172, 2023). "In terms of 1-year RFS, the AUC values of HS and CS were 0.837 and 0.857, respectively, much higher than those of clinical indicators such as AFP or liver cirrhosis, and the CNLC or BCLC staging systems." (PMID 36059627, 2022). "The AFP level increases in some benign liver diseases such as liver cirrhosis (LC) and hepatitis, and a normal serum AFP level is detected in 15–30% of advanced HCC cases." (PMID 35804809, 2022). "The majority of patients were positive for HBV infection (91.2%), and had liver cirrhosis (79.4%) with an AFP concentration below 400 IU/ml (53.7%)." (PMID 35403359, 2022). "What’s more, the 50-LPS maintained a significant prognostic power after adjusting for age, gender, liver cirrhosis, serum AFP level, tumor vascular invasion (VI) and TNM stage and presented a better utility than TNM stage and VI in DCA." (PMID 35193591, 2022). "No obvious difference was found in average age, sex ratio, preoperative tumor marker AFP, tumor size, and number of liver cirrhosis among the four groups (P > 0.05)." (PMID 35634437, 2022). "The current study revealed that COMP ROC-AUC for discriminating HCC patients from those with liver cirrhosis was 0.943, comparable with that of AFP." (PMID 35845304, 2022). "In accordance with the clinical characteristics including serum AFP level, tumor stage, liver cirrhosis and hepatitis virus infection, the patients with HCC obtained from TCGA were classified into various groups." (PMID 35141283, 2022). "The clinical characteristics score of 1 was assigned to the features of age >60 years, male, Child‐Pugh class B/C, liver cirrhosis, serum AFP >400 μg/L, vascular invasion, tumor stage III–IV, and tumor grade 3–4." (PMID 35141283, 2022). "The comparative analysis of the basic data of all patients in various groups showed that there was no statistical difference in the average age, sex ratio, preoperative tumor marker AFP, tumor size, and the number of patients with liver cirrhosis (P > 0.05)." (PMID 35634437, 2022). "This study demonstrated that the Doylestown algorithm, by using readily available clinical parameters, is superior to AFP alone in accurately predicting the development of HCC among patients in the Chinese population with liver cirrhosis." (PMID 35218083, 2022). "While nearly half of the patients operated had histologically proven liver cirrhosis, they were mostly (nearly 99%) Child classification A. The mean tumor size was 35.9 mm and the mean alpha-fetoprotein was 2471.8 ng/mL." (PMID 36169915, 2022). "In the multivariable survival analysis adjusted for the competing risk factors, not only TBS but also alpha-fetoprotein (AFP) level was correlated with prognosis, as were pathologic parameters of tumor aggressiveness and underlying liver cirrhosis." (PMID 36497478, 2022). "We have reported that DJ-1 expression was significantly upregulated in HCC, and the levels correlated with preoperative AFP, liver cirrhosis, vein invasion, differentiation, and Edmondson grade of HCC." (PMID 35770048, 2022). "In our study, the AFP level (>400 ng/ml), presence of liver cirrhosis (confirmed by pathology), and LI-RADS score were revealed to be independent predictors of VEGFR2 expression in HCC patients." (PMID 36313714, 2022).
liver cirrhosis (continued). "More than 60% of patients had liver cirrhosis, and the median alpha-fetoprotein (AFP) was 43.4 ng/ml." (PMID 36248997, 2022). "HBV-HCC patients had higher proportions of positive AFP, liver cirrhosis, advanced BCLC stage, multiple tumor nodules, and vascular tumor thrombus, indicating that HBV not only promotes the occurrence of HCC, but also promotes the recurrence of HCC." (PMID 35800051, 2022). "Compared with classic HCC, patients with fibrolamellar carcinoma were observed to be younger, have a greater proportion of Caucasians and female patients, and be less likely to have positive AFP and liver cirrhosis, which was consistent with previous studies." (PMID 35463333, 2022). "In the present study, local recurrence or progression of HCC, history of liver cirrhosis, and preoperative AFP were found to be independent prognostic factors for overall survival after the first pulmonary metastasectomy." (PMID 33516218, 2021). "There was not a significant difference between two groups in terms of the distribution of sex, histopathologic malignancy, ASA score, AFP, liver cirrhosis, and common pathological characteristics." (PMID 34218803, 2021). "MiR-148a shows good efficacy in identifying early HCC and liver cirrhosis (AUC = 0.891), which is significantly better than AFP (AUC = 0.712), and the combination of miR-122, miR-148a and AFP can further increase AUC to 0.931." (PMID 33869059, 2021). "Univariate analyses demonstrated that serum AFP, liver cirrhosis, DM, Child–Pugh grade, BCLC stage, tumor number, tumor size, histological grade, vascular invasion and cholecystectomy were significantly associated with RFS." (PMID 34945733, 2021). "PON1 is considered as a biomarker for the clinical diagnosis of early HCC and able to distinguish early HCC from liver cirrhosis patients with low AFP levels." (PMID 33495404, 2021). "The prediction power of this prediction model is better than the one we previously developed using clinical variables composed of the levels of HBV DNA load, the presence of liver cirrhosis, the level of AFP, and BCLC stage." (PMID 34534105, 2021). "Many studies demonstrated that advanced age, male gender, tumor size, high AFP level, and the presence of liver cirrhosis are established prognostic factors for HCC." (PMID 34837928, 2021). "TACE+AC provided a clinical benefit for OS in these subgroups as follows: age less than 65 years, ECOG PS score of 1, Child–Pugh classification of B, AFP greater than or equal to 200 ng/ml, male, liver cirrhosis, and hepatitis B infected." (PMID 35174073, 2021). "Liver cirrhosis was observed in 38 patients (22.6%), and high preoperative alpha-fetoprotein (AFP) levels (> 200 ng/mL) were observed in 25 (15.3%) patients." (PMID 34666694, 2021). "This phenomenon was observed in most subgroups, which were classified by recorded survival time, age, country, alpha-fetoprotein (AFP) concentration, liver cirrhosis, and microvascular invasion." (PMID 34869566, 2021). "The most utilized pathological biomarker for HCC screening is alpha-fetoprotein (AFP) which has several limitations, such as having high levels in liver cirrhosis and hepatitis, low sensitivity, and poor selectivity at an early stage of disease." (PMID 34440168, 2021). "This classifier showed higher accuracy than AFP (when using the 20 ng/mL cutoff) to distinguish individuals with HCC from individuals with chronic HBV or liver cirrhosis." (PMID 33918270, 2021). "Our study findings also showed that patients with IMCC had lower a-fetoprotein (AFP) levels, and fewer liver cirrhosis cases compared to patients with HCC (p < 0.001)." (PMID 34848818, 2021). "Local recurrence of HCC, history of liver cirrhosis, and preoperative AFP were found to be independent prognostic factors for overall survival." (PMID 33516218, 2021). "In adults, serum AFP levels greater than 200 ng/mL in patients with liver cirrhosis are a strong indicator of HCC." (PMID 34746648, 2021).
liver cirrhosis (continued). "In the GSE25097 dataset, GINS4 and alpha-fetoprotein (AFP) mRNA expression were both prominently greater in HCC than liver cirrhosis tissues." (PMID 33842367, 2021). "As for data from the GSE63898 dataset, GINS4 and AFP expression in HCC were remarkably elevated compared with liver cirrhosis." (PMID 33842367, 2021). "Local recurrence or progression of HCC, history of liver cirrhosis, and preoperative AFP were found to be independent prognostic factors." (PMID 33516218, 2021). "GINS4 expression was significantly greater in HCC cases with low AFP expression than liver cirrhosis patients from above two datasets." (PMID 33842367, 2021). "Taking lung cancer as an example, attention needs to be paid to the influence of radon, asbestos, second-hand smoke and other factors, while in HCC, attention needs to be paid to hepatitis history, liver cirrhosis and AFP." (PMID 33962640, 2021). "Currently, even after achieving sustained virological response (SVR), patients with HCV liver cirrhosis are recommended for HCC surveillance by ultrasound combined with alpha-fetoprotein (AFP) every 6 months indefinitely." (PMID 33247768, 2021). "Serum levels of AFP that exceed those seen in healthy adults (5 ng/mL) have been reported in some patients with benign hepatic disorders, i.e., viral hepatitis or liver cirrhosis." (PMID 34680245, 2021). "The APEX1 levels were significantly higher in low-AFP expressing HCC patients compared to patients with liver cirrhosis." (PMID 32167932, 2020). "Serum samples from patients with liver cirrhosis in the current study were selected as controls for comparison with HCC patients with normal AFP levels." (PMID 31979338, 2020). "The combination of let-7-a1 and AFP improved the diagnostic accuracy of AFP to detect HCV induced HCC and HCV induced liver cirrhosis." (PMID 32102538, 2020). "On univariate analysis, AFP level, liver cirrhosis and CELSR2 expression were identified as significant factors of recurrence-free survival (RFS)." (PMID 32293343, 2020). "As expected, the AFP levels of liver cirrhosis and HCC patients were similar in these two datasets, and the AUC value of AFP in the GSE25097 and GSE63898 datasets were not statistically significant." (PMID 32167932, 2020). "High serum AFP level can be seen in patients with liver cirrhosis (up to 47%) and chronic active hepatitis (up to 58%)." (PMID 32986366, 2020). "The performance of AFP in distinguishing patients with HCC from liver cirrhosis patients was assessed using receiver-operating characteristic (ROC) curves." (PMID 33357229, 2020). "We selected Trim22 for immunoblotting analysis using patients’ sera and confirmed lower expression in HCC patients with normal AFP than liver cirrhosis controls." (PMID 31979338, 2020). "In our series, liver cirrhosis, which is usually accompanied by portal hypertension, was major predictor requiring complementary AFP screening." (PMID 32845895, 2020). "Multivariate analysis showed AFP level > 200 ng/mL (p = 0.001), liver cirrhosis (p = 0.004), TNM stage III and IV (p < 0.001), and HCC with β-catenin (high) and Chibby (low) (p = 0.012) were significantly associated with recurrent HCC." (PMID 32192213, 2020). "Aside from the ALBI grade, we also showed that age, DM, AFP, platelet count, and liver cirrhosis are important predictors of HCC recurrence." (PMID 32350365, 2020). "It is clear from this figure that HCC with normal AFP levels and liver cirrhosis can be differentiated by the concurrent use of multiple HCC biomarker candidates, such as those developed in this study." (PMID 31979338, 2020). "In all, 77.4% (106/137) of the patients had liver cirrhosis, and 29.9% (41/137) of the patients had an AFP level > 400 ng/ml." (PMID 33129301, 2020). "Both APEX1 and AFP expression was significantly higher in HCC tissues compared to liver cirrhosis samples." (PMID 32167932, 2020).
liver cirrhosis (continued). "The comparison of clinicopathologic characteristics among these three classifications showed that the increase of tumor size was associated with the increase of α-fetoprotein (AFP), microvascular invasion (MVI), tumor differentiation, and liver cirrhosis." (PMID 32709254, 2020). "The model included features in CPTAC: gender, age, tumor differentiation, history of liver cirrhosis, number of tumors, tumor size, tumor thrombus, tumor encapsulation, HBcAb, AFP, PTT, TB, ALB, ALT, and GGT." (PMID 32746792, 2020). "HCC patients with low AFP expression cannot be distinguished from those with liver cirrhosis because of low sensitivity of AFP." (PMID 32167932, 2020). "Our serum proteomic analysis revealed that Trim22 in patients with normal AFP levels was reduced to 60% of the expression levels in patients with liver cirrhosis." (PMID 31979338, 2020). "In terms of hepatic variables, cirrhosis of the liver (OR 1.91; 95% CI 1.21–3.00), and Child-Pugh class B liver function (OR 1.69; CI 1.16–2.48) were independent factors related to the AFP group." (PMID 32845895, 2020). "The comparison of clinicopathologic characteristics among these three groups showed that the increase of tumor size was associated with multiple pathobiological features such as AFP, MVI, tumor differentiation, and liver cirrhosis." (PMID 32709254, 2020). "Sera were collected from HCC patients with normal AFP and patients with liver cirrhosis as controls." (PMID 31979338, 2020). "ROC analysis for AFP was performed to differentiate HCC from liver cirrhosis, at the cut-off value of ≥ 132 ng/ml, AFP showed sensitivity of 82.5% and specificity of 100% with AUC of 0.971 (p < 0.001, 95% CI 0.937- 1.000)." (PMID 32102538, 2020). "In our study, BMP1 showed a lower peak intensity in HCC patients with normal AFP levels than liver cirrhosis patients." (PMID 31979338, 2020). "Analysis of the clinicopathologic features indicated that AKR1B10P1 transcription associates with larger HCC tumour diameters, higher serum AFP quantity, advanced TNM stages, higher incidence of liver cirrhosis and tumour microsatellite formation." (PMID 32924268, 2020). "Generally, surveillance with ultrasound (US) and serum alpha-fetoprotein (AFP) measurement are undertaken in high-risk groups of patients, such as those with chronic HBV or HCV hepatitis and those with liver cirrhosis of any etiology." (PMID 33174159, 2020). "Among these, AFP > 20 μg/L, liver cirrhosis, tumor size > 5 cm, multiple tumors, vascular invasion, and tumor recurrence were associated with high CBX3/HP1γ expression (Chi square test P<0.05)." (PMID 31375643, 2019). "FEN1 expression did not significantly correlated with gender, age, tumor multiplicity, TNM stage, pathological grade, HBsAg, liver cirrhosis or serum alpha-fetoprotein (AFP) (P > 0.05)." (PMID 31534853, 2019). "This shows that AFP serum level had greatly increased in the cancer group by 154-fold as compared to the liver cirrhosis group." (PMID 31205886, 2019). "The patient’s history of viral hepatitis B infection, liver cirrhosis and the ɑ-fetoprotein (AFP) level of 14,429.3 ng/ml supported the clinical diagnosis of HCC and laboratory results demonstrated liver function damage status (Child-Pugh class B, Score 8)." (PMID 31703571, 2019). "It was consistent with the results from the previous studies in which patient factors (DM), liver background factor (liver cirrhosis), and tumor factor (vascular invasion, histology stage, and AFP) determined the outcomes of HCC patients." (PMID 31885547, 2019). "ROC curves were performed to determine the diagnostic values and optimum cutoff of GPC3, miR-122 and AFP for early-stage HCC from all controls (LC+CH+HC, patients of liver cirrhosis and chronic hepatitis C carriers and health controls)." (PMID 33817137, 2019). "The AR group included a higher proportion of patients with large tumors, multiple tumors, liver cirrhosis and high AFP levels than the NAR group." (PMID 31417639, 2019).
liver cirrhosis (continued). "Compared to HCC patients, ICC patients had significantly lower proportions of positive HBsAg, positive HBV DNA, the presence of liver cirrhosis, positive AFP, and the presence of MVI and lower male-to-female ratio, the HBV-related parameters." (PMID 31179237, 2019). "None of total CTC or its EMT phenotypes in HCC patients was correlated with clinical characteristics, such as age, sex, HBsAg, Child-Pugh score, liver cirrhosis, AFP, number of tumors, tumor size, vascular invasion and BCLC stage." (PMID 31068623, 2019). "In the Liver cirrhosis group (group B), 53 out of the 237 patients tested positive for elevated AFP (22.4%); 6 tested positive for AFP and CEA (2.5%); 15 tested positive for AFP and CA19-9 (6.8%); and none tested positive for AFP, CA19-9 and CEA (0%)." (PMID 31205886, 2019). "CBX3/HP1γ expression as measured in those assays was associated with malignant clinicopathological characteristics, such as AFP > 20 μg/L, liver cirrhosis, tumor size > 5 cm, multiple tumors, vascular invasion, and tumor recurrence." (PMID 31375643, 2019). "Presence of CRC, liver cirrhosis, elevated baseline alpha-fetoprotein level, and low platelet counts were independent predictors of HCC development in ALD patients." (PMID 30824851, 2019). "The mean serum marker level for AFP in the cancer group was 4336.47±16094.35 ng/L as compared to 28.41±73.17μg/L in the Liver cirrhosis group and <20.00μg/L in the healthy control group." (PMID 31205886, 2019). "Univariable analysis also showed that liver cirrhosis, tumour size, macroscopic multiple tumours, poor differentiation, microvascular invasion, microscopic intrahepatic metastases, AFP and DCP concentration, and low LMR were significant predictors of RFS." (PMID 31388642, 2019). "We revealed that methylation alterations in DNAH17 have a correlation with age, gender, serum AFP level, liver cirrhosis, tumor necrosis, fibrous capsule, and tumor thrombus." (PMID 30575322, 2019). "Other significant baseline risk factors for HCC development included old age, presence of liver cirrhosis, high in alcohol consumption amount, high AFP level, low albumin level, prolonged prothrombin time, and low platelet counts." (PMID 30824851, 2019). "The clinicopathological features included age, gender, hepatitis history, AFP, tumour size, tumour stage, tumour differentiation, vascular invasion, tumour multiplicity, encapsulation, and liver cirrhosis." (PMID 30718977, 2019). "AFP is also frequently elevated in benign liver diseases such as hepatitis and liver cirrhosis, and L3 fraction has been used as a tumor marker for highly specific HCC." (PMID 30203247, 2018). "AFP is also frequently elevated in benign liver diseases such as hepatitis and liver cirrhosis, and L3 fraction has been used as a tumor marker for HCC with high specificity." (PMID 30203247, 2018). "Low expression of NFATc1 was correlated with larger tumor size, advanced tumor‐node‐metastasis (TNM) stage, high serum AFP level, and liver cirrhosis." (PMID 30085405, 2018). "ROC analysis showed this protein has sensitivity of 91% (higher than AFP) and specificity of 66% when used to distinguish HCC from liver cirrhosis (LC, HCC high risk population)." (PMID 30345303, 2018). "Further, the c-statistic was increased from 0.732 in the basic model to 0.772 when putting AFP levels in the prediction model to differentiate HCC patients from liver cirrhosis patients." (PMID 29435160, 2018). "A high expression of FOXC2 was observed in 26 of 84 cases, and expression was significantly correlated with background liver cirrhosis, poor tumor differentiation, high serum AFP, and elevated cell proliferation markers." (PMID 29801468, 2018). "Ten variables, including BMI, AST, ALT, liver cirrhosis, AFP level, CAR level, tumor size, macrovascular invasion, tumor number, and extra‐hepatic metastases, were associated with OS (Table [Link], [Link], [Link], [Link])." (PMID 30259688, 2018).